STUB1 (STIP1 homology and U-box containing protein 1)
Description:
E3 ubiquitin-protein ligase which targets misfolded chaperone substrates towards proteasomal degradation. Plays a role in the maintenance of mitochondrial morphology and promotes mitophagic removal of dysfunctional mitochondria; thereby acts as a protector against apoptosis in response to cellular stress (By similarity). Negatively regulates vascular smooth muscle contraction, via degradation of the transcriptional activator MYOCD and subsequent loss of transcription of genes involved in vascular smooth muscle contraction (By similarity). Promotes survival and proliferation of cardiac smooth muscle cells via ubiquitination and degradation of FOXO1, resulting in subsequent repression of FOXO1-mediated transcription of pro-apoptotic genes. Ubiquitinates ICER-type isoforms of CREM and targets them for proteasomal degradation, thereby acts as a positive effector of MAPK/ERK-mediated inhibition of apoptosis in cardiomyocytes. Inhibits lipopolysaccharide-induced apoptosis and hypertrophy in cardiomyocytes, via ubiquitination and subsequent proteasomal degradation of NFATC3. Collaborates with ATXN3 in the degradation of misfolded chaperone substrates: ATXN3 restricting the length of ubiquitin chain attached to STUB1/CHIP substrates and preventing further chain extension. Ubiquitinates NOS1 in concert with Hsp70 and Hsp40. Modulates the activity of several chaperone complexes, including Hsp70, Hsc70 and Hsp90. Ubiquitinates CHRNA3 targeting it for endoplasmic reticulum-associated degradation in cortical neurons, as part of the STUB1-VCP-UBXN2A complex. Ubiquitinates and promotes ESR1 proteasomal degradation in response to age-related circulating estradiol (17-beta-estradiol/E2) decline, thereby promotes neuronal apoptosis in response to ischemic reperfusion injury (By similarity). Mediates transfer of non-canonical short ubiquitin chains to HSPA8 that have no effect on HSPA8 degradation. Mediates polyubiquitination of DNA polymerase beta (POLB) at 'Lys-41', 'Lys-61' and 'Lys-81', thereby playing a role in base-excision repair: catalyzes polyubiquitination by amplifying the HUWE1/ARF-BP1-dependent monoubiquitination and leading to POLB-degradation by the proteasome. Mediates polyubiquitination of CYP3A4. Ubiquitinates EPHA2 and may regulate the receptor stability and activity through proteasomal degradation. Acts as a co-chaperone for HSPA1A and HSPA1B chaperone proteins and promotes ubiquitin-mediated protein degradation. Negatively regulates the suppressive function of regulatory T-cells (Treg) during inflammation by mediating the ubiquitination and degradation of FOXP3 in a HSPA1A/B-dependent manner. Catalyzes monoubiquitination of SIRT6, preventing its degradation by the proteasome. Likely mediates polyubiquitination and down-regulates plasma membrane expression of PD-L1/CD274, an immune inhibitory ligand critical for immune tolerance to self and antitumor immunity. Negatively regulates TGF-beta signaling by modulating the basal level of SMAD3 via ubiquitin-mediated degradation. Mediates ubiquitination of RIPK3 leading to its subsequent proteasome-dependent degradation. May regulate myosin assembly in striated muscles together with UBE4B and VCP/p97 by targeting myosin chaperone UNC45B for proteasomal degradation. Ubiquitinates PPARG in macrophages playing a role in M2 macrophages polarization and angiogenesis (By similarity).
Synonyms: CHIP; UBOX1; SDCCAG7; HSPABP2; NY-CO-7; SCA48; SCAR16
Tractability: Small molecule: a structure with a bound ligand is known. PROTAC: UniProt records ubiquitination sites on it; ubiquitination databases record sites on it; its protein half-life has been measured.
Target class: Enzyme; Transferase
Gene: Protein-coding gene on chromosome 16 (679,980 to 682,870, forward strand). Ensembl gene ENSG00000103266.
Subcellular location: Cytoplasm; Nucleus; Mitochondrion
Subcellular location (Human Protein Atlas): Cytosol; Nucleoplasm
Pathways (Reactome):
Signal Transduction: Downregulation of ERBB2 signaling; Downregulation of TGF-beta receptor signaling; Regulation of PTEN stability and activity; Regulation of TNFR1 signaling
Programmed Cell Death: RIPK1-mediated regulated necrosis; Regulation of necroptotic cell death
Gene expression (Transcription): Regulation of RUNX2 expression and activity
Immune System: Antigen processing: Ubiquitination & Proteasome degradation
Gene Ontology:
Molecular function: enzyme binding; G protein-coupled receptor binding; heat shock protein binding; Hsp70 protein binding; Hsp90 protein binding; kinase binding; misfolded protein binding; protein binding; protein homodimerization activity; protein-folding chaperone binding; R-SMAD binding; SMAD binding; TPR domain binding; ubiquitin protein ligase activity; ubiquitin protein ligase binding; ubiquitin-protein transferase activity; protein-macromolecule adaptor activity; tau protein binding; ubiquitin-ubiquitin ligase activity
Biological process: cellular response to misfolded protein; ERAD pathway; negative regulation of smooth muscle cell apoptotic process; negative regulation of transforming growth factor beta receptor signaling pathway; positive regulation of chaperone-mediated protein complex assembly; positive regulation of ERAD pathway; positive regulation of proteasomal ubiquitin-dependent protein catabolic process; positive regulation of protein ubiquitination; positive regulation of proteolysis; proteasome-mediated ubiquitin-dependent protein catabolic process; protein autoubiquitination; protein K63-linked ubiquitination; protein monoubiquitination; protein polyubiquitination; protein quality control for misfolded or incompletely synthesized proteins; protein stabilization; protein ubiquitination; regulation of glucocorticoid metabolic process; regulation of protein stability; ubiquitin-dependent protein catabolic process; cellular response to heat; cellular response to hypoxia; ERBB2 signaling pathway; MAPK cascade; negative regulation of peroxisome proliferator activated receptor signaling pathway; and 11 more
Cellular component: cytoplasm; cytosol; endoplasmic reticulum; nuclear inclusion body; nucleoplasm; nucleus; protein folding chaperone complex; ubiquitin ligase complex; mitochondrion; ubiquitin conjugating enzyme complex; Z disc
Genetic constraint (gnomAD): Loss-of-function variants: 37 observed, 37.62 expected, observed/expected ratio (o/e) 0.98, 90% interval 0.76 to 1.29. The synonymous counts are far from expectation, so gnomAD's model fits this gene poorly and the ratio says little. Missense variants: 460 observed, 405.53 expected, observed/expected ratio (o/e) 1.13, 90% interval 1.05 to 1.23. Synonymous variants: 246 observed, 166.09 expected, observed/expected ratio (o/e) 1.48, 90% interval 1.33 to 1.65.
Homologues: Orthologues: chimpanzee STUB1 (100% identical), macaque STUB1 (100% identical), dog STUB1 (98% identical), mouse Stub1 (98% identical), rat Stub1 (98% identical), guinea pig STUB1 (97% identical), pig STUB1 (97% identical), tropical clawed frog stub1 (81% identical), zebrafish stub1 (75% identical), Drosophila melanogaster STUB1 (52% identical), Caenorhabditis elegans chn-1 (36% identical). Paralogues in human: SPAG1 (23% identical), RPAP3 (20% identical), UNC45A (19% identical), UNC45B (18% identical), STIP1 (17% identical), SPATA16 (17% identical), SGTA (17% identical), SGTB (17% identical), ST13 (17% identical), TTC4 (17% identical), TTC1 (16% identical), DNAAF4 (16% identical), and 6 more.
Diseases named in the same sentence as STUB1 in open-access papers:
STUB1 is named in the same sentence as 217 diseases in open-access papers, as found by Europe PMC text mining. Sharing a sentence is not in itself a finding about the gene and the disease. The quoted sentences say what the papers report.
breast cancer (57 papers, 1986 to 2026). A primary or metastatic malignant neoplasm involving the breast. "Human prostate and breast cancer cells with STUB1 deletion were also susceptible to cytokine-induced growth inhibition." (PMID 35982220, 2022). "A positive correlation between FOXM1 and TOP2A expression was found in patients with breast cancer undergoing EC-T chemotherapy, both negatively correlated with STUB1, whose higher expression levels were linked to increased pathologic complete response (pCR) rates." (PMID 41851614, 2026). "In a breast cancer xenograft model, STUB1 suppressed tumor growth and improved doxorubicin sensitivity." (PMID 41851614, 2026). "We shortlisted DU145 (prostate), PC-3 (prostate) and MCF7 (ER+/HER2-breast) as model cell lines for the study, due to the overexpression of STUB1 in prostate and breast cancer suggested by analysis of the TCGA dataset." (PMID 35982220, 2022). "In colorectal cancer, breast cancer, and gastric cancer, STUB1 functioned as a tumor suppressor and impaired the malignancy of colorectal, breast, and gastric cancer cells by inactivating NF-κB signaling." (PMID 34262937, 2021). "Studies have indicated that the loss of nuclear, but not cytoplasmic, STUB1 is associated with increased tumor aggressiveness and reduced survival in patients with breast cancer." (PMID 40859326, 2025). "Previous research has shown that the E3 ligase STUB1 promotes the ubiquitination of the rate-limiting enzyme PGK1, thereby inhibiting the Warburg effect, tumor growth, and metastasis in breast cancer." (PMID 38993561, 2024). "In breast cancer, TRIM6 was demonstrated to interact with STUB1 (STIP1 homology and U-box containing protein 1) and mediate its degradation thereby promoting YAP1 signaling." (PMID 36261847, 2022). "Moreover, immunohistochemical staining was conducted to assess STUB1 and TOP2A expression levels, as well as their predictive roles in the efficacy of neoadjuvant chemotherapy in individuals diagnosed with breast cancer." (PMID 41851614, 2026). "Consequently, STUB1 is downregulated in human CRC, breast cancer, and gastric cancer." (PMID 35920319, 2023).
Ataxia (34 papers, 2012 to 2025). Ataxia refers to impaired coordination of voluntary muscle movement. "So far, no STUB1 or HSPA mutants have been associated with neuromuscular diseases, but mutations in STUB1 have been recognized as cause of spinocerebellar ataxia." (PMID 40243504, 2025). "Differently from BAG3 and HSPB8, mutations in STUB1 have been linked to spinocerebellar ataxias, diseases characterized by degeneration of the cerebellum and cognitive impairment." (PMID 36594740, 2023). "Spinocerebellar ataxias related to STUB1 mutations display a recessive (SCAR16) or dominant (SCA48) inheritance pattern and are variable in terms of onset, progression, and symptoms." (PMID 36594740, 2023). "These include the RBR E3 ligase Parkin, which is a major source of recessive mutations that give rise to Parkinson’s disease and the RING E3 ligase CHIP/STUB1, which is mutated in several subcategories of hereditary spinocerebellar ataxia." (PMID 36578786, 2022). "In 2019, heterozygous STUB1 mutations identified in patients with ataxia uncovered a new classification of autosomal dominant spinocerebellar ataxia, SCA48." (PMID 34831344, 2021). "Subsequent studies reported heterozygous STUB1 mutations in several families with ataxia and cognitive–psychiatric disorder, often associated with other features such as dystonia, parkinsonism, chorea, and endocrine dysfunction." (PMID 34070858, 2021). "We investigated the clinical, genetic and functional characteristics of STUB1 mutations identified from a Taiwanese ataxia cohort." (PMID 34565360, 2021). "In this study, we identified a novel heterozygous frameshift STUB1 mutation, c.832del (p.Glu278fs), in an autosomal-dominant three-generational ataxia family among a cohort of patients manifesting cerebellar ataxia syndrome." (PMID 34565360, 2021). "Heterozygous STUB1 mutations cause dominantly inherited cerebellar ataxia SCA48, and despite its recent description, SCA48 has emerged as one of the more frequent subtypes of SCA." (PMID 34070858, 2021). "A recent study used Sanger sequencing to explore STUB1 mutations in 512 Taiwanese families with cerebellar ataxia." (PMID 34565360, 2021). "Since the initial association of STUB1 with an autosomal-dominant form of spinocerebellar ataxia (SCA48) in 2018, 34 SCA48 patients originating from 17 families have been reported." (PMID 33811518, 2021). "Several mutations in the STUB1 gene have been reported in patients with recessive and dominant cerebellar ataxias (CA)." (PMID 34630034, 2021). "Using whole-exome sequencing, we identified a mutation in STUB1 in two patients initially diagnosed with ataxia and hypogonadism." (PMID 31619515, 2019). "Mutations in the STUB1 gene result in Gordon Holmes syndrome, which is characterized by ataxia and hypogonadism." (PMID 31749756, 2019). "Subsequently, numerous clinical reports identified STUB1 mutations in patients with ataxia, confirming our initial identification of a new disease (3, –, 10)." (PMID 31619515, 2019). "The approximate frequency estimate of 2.3% confirms our previous data from an independent early-onset ataxia cohort that STUB1 is a recurrent, but overall rare cause of early-onset ataxia (previous frequency estimate: 1.8%;)." (PMID 28193273, 2017). "For example, in one index patient hypogonadotropic hypogonadism was identified concomitant to ataxia, leading to the notion that STUB1 is a cause of Gordon Holmes syndrome." (PMID 28193273, 2017). "Most of the reported individuals with STUB1 mutations had a relatively circumscribed phenotype, mainly consisting of an ataxia syndrome with involvement of only one or two additional neurologic systems." (PMID 28193273, 2017). "Trehalose, a disaccharide, improves the deteriorating changes taking place in patients with ataxia due to a genetic mutation in STUB1/CHIP." (PMID 27757073, 2016).
Ataxia (continued). "Mutation in STUB1 gene is one of the genetic causes of the Gordon Holmes syndrome, an autosomal recessive type of hereditary cerebellar ataxia in association with hypogonadotropic hypogonadism." (PMID 27757073, 2016). "We followed up on this by identifying another mutation in STUB1 in the only family we have registered in our local database, presenting with a combination of ataxia and hypogonadotrophic hypogonadism, as well as additional symptoms possibly related to disease." (PMID 25258038, 2014). "We identified 3 ataxia patients (3/167 = 1.8%) with 4 novel missense mutations in STUB1, including 3 mutations in its tetratricopeptide-repeat domain." (PMID 24742043, 2014). "Just recently, Shi and colleagues reported one family with another homozygous STUB1 mutation as the cause of ataxia and hypogonadism in two siblings of a consanguineous marriage." (PMID 25258038, 2014). "All three index patients carrying two recessive STUB1 mutations presented with cerebellar ataxia as the main and initial feature (for clinical details)." (PMID 24742043, 2014). "Here we have identified a de novo mutation in the STUB1 gene that causes ataxia." (PMID 35398354, 2022). "It remains unclear, however, why some STUB1 mutations cause recessive ataxias with apparently unaffected heterozygous parents, while similar mutations cause dominant SCA48 in other families." (PMID 34070858, 2021). "However, it was nearly 15 years after the discovery of CHIP when the first disease-causing coding mutation in the gene that encodes CHIP (STUB1) was identified in a family with two siblings with early-onset ataxia." (PMID 34831344, 2021). "Accordingly there is a rational base for the implementation of well-designed clinical trials in groups of STUB1 gene patients, with autosomal dominant, autosomal recessive or even sporadic resembling ataxias, as more and more families are discovered with mutations impairing CHIP function." (PMID 25259530, 2014). "However, these recent studies linking STUB1 mutations to various forms of ataxia are the first indications that CHIP is directly involved in the progression of a human disease." (PMID 27081508, 2014). "In some cases, SCA associated with STUB1 mutations has been considered one pathological feature of a multisystemic disease, in which ataxia may be accompanied by hypogonadism (as in Gordon Holmes syndrome), pyramidal tract damage, dementia and hyperkinetic movement disorders." (PMID 36594740, 2023). "Moreover, we found that Stub1 mutants discovered in Ataxia patients are deficient in their ability to trigger this form of pexophagy, suggesting an interesting link between defective peroxisomal quality control and Ataxia." (PMID 33077711, 2020). "The inactivating mutation at the p.T246M locus of the STUB1 gene culminates in CHIP U-box inactivation and reduced cerebral CHIP levels, thereby presenting typical clinical manifestations of ARCA-induced cerebellar ataxia." (PMID 39806097, 2025). "Autosomal dominant spinocerebellar ataxia type 48 (SCA48) is a newly identified subtype of SCA, marked by early-onset ataxia and cognitive impairment, and is associated with mutations in the STIP1 homology and U-box-containing protein 1 (STUB1) gene." (PMID 39707479, 2024). "When encountering patients with cerebellar ataxia, especially those with Huntington’s disease-like symptoms, genetic testing for STUB1 as well as TBP should be conducted for diagnosis of SCA17-DI, even in cases of sporadic or autosomal recessive inheritance." (PMID 36476347, 2022). "Future genetic screening of STUB1 in a large cohort of ataxia families in different ethnicities is needed to evaluate the frequency of SCAR16 or SCA48 in patients with familial ataxia syndrome." (PMID 34565360, 2021). "The recent finding that STUB1 mutations also can cause the dominant spinocerebellar ataxia disease, SCA48, emphasizes that the underlying mechanisms of STUB1-mediated ataxias remain poorly understood." (PMID 34630034, 2021).